CYSLTR1 (cysteinyl leukotriene receptor 1)
Description:
Receptor for cysteinyl leukotrienes mediating bronchoconstriction of individuals with and without asthma. Stimulation by LTD4 results in the contraction and proliferation of smooth muscle, edema, eosinophil migration and damage to the mucus layer in the lung. This response is mediated via a G protein that activates a phosphatidylinositol-calcium second messenger system. The rank order of affinities for the leukotrienes is LTD4 >> LTE4 = LTC4 >> LTB4.
Synonyms: CYSLT1; CysLT(1); CYSLT1R; CYSLTR; HMTMF81
Tractability: Small molecule: an approved drug acts on it; a structure with a bound ligand is known; a high-quality ligand is known; it belongs to a druggable protein family. Antibody: its Gene Ontology location is reachable by antibodies, with high confidence; UniProt places it where antibodies can reach, with medium confidence; UniProt predicts a signal peptide or a membrane-spanning region. PROTAC: a small molecule that binds it is known.
Target class: Leukotriene receptor; Small molecule receptor (family A GPCR); Membrane receptor; Lipid-like ligand receptor (family A GPCR); Family A G protein-coupled receptor
Chemical probes: ZAFIRLUKAST (high quality)
Gene: Protein-coding gene on chromosome X (78,271,468 to 78,327,691, reverse strand). Ensembl gene ENSG00000173198.
Subcellular location: Cell membrane
Pathways (Reactome):
Disease: LTC4-CYSLTR mediated IL4 production; Potential therapeutics for SARS
Signal Transduction: G alpha (q) signalling events; Leukotriene receptors
Gene Ontology:
Molecular function: cysteinyl leukotriene receptor activity; galanin receptor activity; leukotriene receptor activity; G protein-coupled receptor activity
Biological process: defense response; neuropeptide signaling pathway; positive regulation of cytosolic calcium ion concentration; respiratory gaseous exchange by respiratory system; G protein-coupled receptor signaling pathway; leukotriene signaling pathway
Cellular component: membrane; plasma membrane
Homologues: Orthologues: chimpanzee CYSLTR1 (99% identical), macaque CYSLTR1 (97% identical), dog CYSLTR1 (93% identical), rabbit CYSLTR1 (91% identical), pig CYSLTR1 (91% identical), guinea pig CYSLTR1 (88% identical), mouse Cysltr1 (88% identical), rat Cysltr1 (87% identical), tropical clawed frog cysltr1 (62% identical), zebrafish cysltr1 (58% identical), Caenorhabditis elegans gnrr-4 (18% identical). Paralogues in human: CYSLTR2 (33% identical), LPAR6 (30% identical), LPAR4 (28% identical), GPR17 (27% identical), P2RY10 (27% identical), P2RY8 (26% identical), GPR18 (26% identical), F2R (25% identical), F2RL1 (25% identical), F2RL2 (24% identical), GPR4 (24% identical), GPR65 (22% identical), and 4 more.
Diseases named in the same sentence as CYSLTR1 in open-access papers:
CYSLTR1 is named in the same sentence as 125 diseases in open-access papers, as found by Europe PMC text mining. Sharing a sentence is not in itself a finding about the gene and the disease. The quoted sentences say what the papers report.
asthma (80 papers, 2006 to 2026). "Montelukast, a cysLTR1 antagonist, is widely used for asthma treatment as an alternative to or in association with Inhaled Corticosteroids (ICS) in steps 3 or 4 of allergic rhinitis treatment, and in the prophylaxis of exercise-induced asthma." (PMID 37109111, 2023). "In our Nb infection model, lung cells and a fraction of proximal clustering MLN cells also express genes associated with asthma or involved in pathways targeted by drugs for asthma treatment like Cysltr1, Plac8, or Adam8." (PMID 35950748, 2022). "CysLTR1 has been implicated in a number of inflammatory diseases, including asthma and allergic rhinitis." (PMID 32179525, 2020). "Variation in the CYSLTR1 gene modulates asthma risk as well as adenoid hypertrophy progression, and it has been implicated in the disease outcome of colorectal, prostate, and squamous cell carcinoma 17-21." (PMID 32038103, 2020). "Recently, authors have demonstrated that health effects of acute particulate exposure on asthma were associated with changes in cysteinyl leukotriene (CysLTR1) expression and methylation of CpG sites on CysLTR1 and leukotriene C4 synthase genes." (PMID 32411804, 2020). "Knockout of Cysltr1 prevents mice from irritant-induced asthma and also reduces colitis-associated colon cancer." (PMID 31620001, 2019). "This group reported that the LTC4S -444A > C [c.-444A > C] gene polymorphism, in conjunction with the rare c.-819T > G, c.2078C > T or c.2534A > G alleles of the CYSLTR1 gene, was associated with aspirin intolerant asthma." (PMID 27990118, 2016). "Taken together, many studies suggest that transcriptionally active CYSLTR1 variants influence the onset and severity of asthma associated endophenotypes such as atopy." (PMID 27990118, 2016). "CYSLTR1 variants, such as the 927 T > C variant (rs320995), have been associated with asthma in out-bred populations." (PMID 27990118, 2016). "Asthma prevalence is related to the chromosomal gene Cysteinyl Leukotriene Receptor-1 (CYSLTR1) and it has been suggested that the underlying genetic pathogenesis of asthma is sex-specific." (PMID 24204876, 2013). "We have previously investigated the role of polymorphic variation in the genes of the 5-lipoxygenase pathway e.g. ALOX5, LTC4S, CYSLTR1 in asthma and allergy susceptibility and as determinants of clinical responses to therapies targeting this pathway." (PMID 22206291, 2011). "We have also previously observed that some clinical features of severe asthma were associated with the minor [TCGC] haplotype of CYSLTR1 promoter SNPs in severe asthmatic women." (PMID 20003473, 2009). "CYSLTR1 promoter haplotypes were associated with aspirin-sensitive asthma in a Korean population, but again only in male patients." (PMID 18197984, 2008). "Montelukast is an antagonist that competitively inhibits only CysLTR1 and has previously been reported to reduce the risk of lung, colon, liver, and breast cancer in a dose-dependent manner when taken orally for the treatment of asthma." (PMID 39064957, 2024). "CYSLTR1 encodes a protein that is a second receptor for cysteinyl leukotrienes and is thought to be the main receptor mediating cysteinyl leukotriene receptor smooth-muscle contraction and inflammatory cell cytokine production in asthma." (PMID 35865633, 2022). "Future studies should investigate whether asthma-obesity related genes are associated with sex-specific asthma-related genes such as CYSLTR1." (PMID 24204876, 2013). "Genetic variants of CYSLTR1 promoter might be associated with gender specific expression of CysLT1 transcripts in patients with asthma." (PMID 20003473, 2009). "Genetic variants of CYSLTR1 promoter might be associated with gender specific expression of CysLT1 alternative transcripts in patients with asthma." (PMID 20003473, 2009). "Clinical research has confirmed that patients with asthma have significantly higher levels of CysLTR1 miRNA expression and protein-positive cell counts than healthy individuals do." (PMID 41557720, 2026).
asthma (continued). "We identified 31 potential targets associated with AFB1 exposure and asthma, including PTGS2, ADRB2, CysLTR1, PTGS1, and others." (PMID 41557720, 2026). "CysLTR1 plays a role in the pathogenesis of asthma and allergic rhinitis, both of which often follow atopic dermatitis in the clinical progression known as the “atopic march”." (PMID 40612737, 2025). "Previous studies have shown that inflammatory cytokines upregulate CysLTR1 in conditions such as asthma." (PMID 40847739, 2025). "CysLTR1 expression is reportedly increased in the airway mucosa of asthma patients, particularly during exacerbations, and an important regulator of mucus secretion, eosinophil recruitment, and airway inflammation, which are all hallmarks of asthma." (PMID 41356350, 2025). "Montelukast (MTK), a potent antagonist of cysteinyl leukotriene receptor 1 (CysLTR1), is widely used to treat asthma and allergic rhinitis." (PMID 38256958, 2024). "Inhibitors of CysLTR2 and CysLTR1 are currently being evaluated in Phase II trials as asthma treatments." (PMID 39247132, 2024). "This variability is often associated with a significantly altered response to montelukast, a cysLTR1 antagonist widely used for the treatment of asthma or allergic rhinitis." (PMID 37109111, 2023). "Long-term zafirlukast treatment reduces cancer risks in cohorts of asthma patients and CysLTR1 antagonists have been shown to control tumor growth and cell death in a variety of tumor entities." (PMID 35408930, 2022). "MK is an orally active CysLTR1 antagonist that blocks the action of LTD4 used in the prophylaxis of asthma and management of various inflammatory disorders." (PMID 36145367, 2022). "The CysLTs receptor (CysLTR1) has a relevant effect in the onset of asthma, and montelukast is a CysLTR1 antagonist employed for the therapy of asthma." (PMID 36009422, 2022). "MK and other CysLTs only block CysLTR1; however, gemilukast inhibits both CysLTR1 and CysLTR2, which can be effective in the management of asthma." (PMID 36145367, 2022). "Montelukast is a cysteinyl leukotriene receptor 1 (CysLTR1) antagonist widely used to suppress the inflammatory response in asthma and allergic rhinitis." (PMID 34565285, 2021). "Cysteinyl-leukotriene receptor-1 antagonists (e.g. montelukast) have a modest suppressive effect in adults with asthma." (PMID 34646341, 2021). "The most interesting candidate is probably the cysteinyl leukotriene receptor 1 (CYSLTR1) gene, located on chromosome Xq21.1, which has been implicated in several allergic disorders, including asthma." (PMID 34884340, 2021). "Like the CYSLTR1 gene, LTC4S polymorphisms were associated with asthma risk and drug responsiveness in different ethnic populations 42-45." (PMID 32038103, 2020). "Montelukast was developed as a highly selective CysLTR1 antagonist, which is currently used and approved for the treatment of asthma, allergic rhinitis, exercise-induced bronchoconstriction, and acetylsalicylic acid-sensitive asthmatic patients." (PMID 33392263, 2020). "The cysteinyl leukotriene receptor 1 (CysLTR1) is a G-protein coupled receptor (GPCRs) and its interaction with CysLTs plays a central role in the pathophysiology of asthma and other inflammatory diseases." (PMID 31973226, 2020). "Cysteinyl leukotriene receptor 1 antagonists (CysLT1RA) are frequently used as add-on medication for the treatment of asthma." (PMID 30949053, 2019). "Montelukast, as a selective inhibitor of Cysltr1, is clinically used for the prevention and long-term treatment of asthma." (PMID 31620001, 2019). "The cysteinyl leukotriene receptor 1 antagonists (CysLT1RA) montelukast, zafirlukast and pranlukast were initially developed for the treatment of asthma." (PMID 30949053, 2019). "More importantly, 11 mRNAs were overlapped in our sequencing data, MalaCards database and asthma-associated genes, including IL4, IL-10, MMP9, VCAM-1, Il1rl1, Alox5, Il1rn, Ccr3, Cysltr1, Epx, and Ccl24." (PMID 31231429, 2019).
asthma (continued). "PRK is a known inhibitor of cysteinyl leukotriene receptor‐1 (CysLTR1), on the mammalian cells and is used for treatment of asthma." (PMID 29483133, 2018). "The putative co-inheritance of CYSLTR1 and CYSLTR2 variants suggest a mode of asthma inheritance that is the result of epistasis." (PMID 27990118, 2016). "The associations of the CYSLTR1 and CYSLTR2 genes with atopy and asthma provided the rationale for studying the functional consequences of these variants with respect to agonist and their possible contribution to the atopy phenotype." (PMID 27990118, 2016). "CysLTR1 antagonists have a significant role to play in airway disorders, in particular allergic rhinitis (AR) and/or asthma." (PMID 24971371, 2014). "However, our data suggest that indeed CYSLTR1 gene might be implicated in asthma pathogenesis at least by differential expression of CysLT1 alternative transcripts in various haplotypes and in sex-related manner, but the exact mechanisms remain to be clarified." (PMID 20003473, 2009). "In summary, still little is known about factors involved in the processes of CYSLTR1 transcription, alternative splicing, and their influence on the final CysLT1 receptor protein expression and further correlation with the asthma phenotype." (PMID 20003473, 2009). "A study of a Spanish population found that the combination of 927T of CYSLTR1 and -444A of the leukotriene C4 synthase gene was less common in male patients with asthma than in controls." (PMID 18197984, 2008). "Cysteinyl leukotrienes are bronchoconstrictors and proinflammatory mediators of the asthma response that act through two G protein-coupled receptors: cysteinyl leukotriene receptor-1 (CYSLTR1) and CYSLTR2." (PMID 18197984, 2008). "CysLTR1 can also bind to CysLTs, leading to increased calcium ion concentrations within Th2 cells, promoting their migration to inflammatory sites, and exacerbating the inflammatory response in asthma." (PMID 41557720, 2026). "Thus, Cysltr1 plays a pathophysiological role in asthma, and chronic treatments with Cysltr1 inhibitors such as montelukast (MTK) and zafirlukast (ZK) are used to prevent allergic reactions." (PMID 39891615, 2025). "Similarly, the CysLTR1 antagonist montelukast was recently found to alleviate asthma-exacerbated cognitive deficits in APP/PS1 mice." (PMID 40507859, 2025). "CYSLTR1 (Cysteinyl Leukotriene Receptor 1) is a key receptor in the leukotriene signaling pathway and plays a central role in allergic inflammatory diseases such as asthma." (PMID 40444276, 2025). "Montelukast, a cysteinyl leukotriene receptor 1 (CysLTR1) antagonist, and zileuton, a 5‐lipoxygenase inhibitor, are widely used in chronic inflammatory diseases such as asthma, where they provide a targeted means to reduce inflammation without broad immunosuppressive effects." (PMID 40847739, 2025). "Most importantly, we identified zafirlukast, a synthetic antagonist of the cysteinyl leukotriene receptor 1 (CysLTR1) commonly used to treat asthma, which was able to differentiate SBGS into brown adipocytes to a similar extent to the positive control rosiglitazone." (PMID 36005620, 2022). "Montelukast is a CysLTR1 antagonist clinically used for the treatment of asthma." (PMID 31973226, 2020). "Since the CYSLTR1is the target for anti-asthma drugs such as montelukast, the CYSLTR1 SNPs may provide an opportunity to examine the amino acid residues necessary to the structure-activity relationships that define drug action." (PMID 27990118, 2016). "Studies using cysLTR1 antagonists and other leukotriene modifiers have suggested that these agents may be of benefit in patients with aspirin-intolerant asthma." (PMID 24971371, 2014). "There have been relatively few studies of cysLTR1 antagonists in the elderly with asthma." (PMID 24971371, 2014).
asthma (continued). "To test this hypothesis, we analyze the expression of CysLT1 alternative transcripts in patients with asthma and in healthy control group with the relevance to the CYSLTR1 gene promoter polymorphisms." (PMID 20003473, 2009). "We identified 31 potential targets that may be associated with AFB1 exposure and asthma, including PTGS2, ADRB2, CysLTR1, PTGS1, and others, which play crucial roles in airway inflammation, smooth muscle contraction, immune regulation, and inflammatory mediator production." (PMID 41557720, 2026). "Similarly, the contribution of CYSLTR1 and CYSLTR2 alleles may contribute additively or synergistically to asthma in association with other risk alleles and environmental factors." (PMID 27990118, 2016). "This section will review the role of cysLTR1 antagonists in allergic rhinitis (AR) and asthma, including pediatric, adult, and elderly patients, as well as the various subsets of asthmatic patients, such as those with AR, those with aspirin-sensitive asthma and those with exercise-induced asthma." (PMID 24971371, 2014). "Montelukast (MLK) is a cysteinyl leukotriene receptor 1 (CysLT1R) and G protein-coupled receptor 17 (GPR17) antagonist, approved as adjuvant therapy for asthma in both children and adults." (PMID 36782185, 2023). "The cysteinyl leukotriene receptor 1 (CYSLTR1) antagonists and the inhibitor of ALOX-5 were the main drugs that were used to block the effect of cysteinyl leukotriene in asthma." (PMID 29751569, 2018). "The study of CYSLTR1 and CYSLTR2 gene variability in asthma, therefore, must be considered in the context of the genetic polymorphisms found within the synthesis pathway genes as well as genes that modify patient response to LTMs." (PMID 27990118, 2016). "CysLTs exert their biological actions by binding two types of G-protein-coupled seven-transmembrane receptors: cysteinyl leukotriene receptor 1 (CysLTR1; MIM 300201), which is sensitive to the asthma drugs montelukast, zafirlukast and pranlukast and CysLTR2." (PMID 19840403, 2009). "The PPI network, which had 31 nodes and 68 edges, was constructed using the intersection of AFB1 and asthma target genes In this study, PTGS2, ADRB2, MMP9, CysLTR1, and PTGS1 were the top five targets according to degree value, representing the hub targets of AFB1-induced asthma." (PMID 41557720, 2026). "Montelukast is a selective antagonist of CYSLTR1, which can ameliorate leukotriene (LTD)-induced bronchoconstriction and significantly reduce both the early and late airway responses to allergens, rendering it effective against allergic rhinitis and asthma." (PMID 38617532, 2024). "It is therefore not surprising that the cysLTR1 antagonists have enjoyed a well-established role in the treatment of patients with asthma for a considerable number of years, with efficacy and safety confirmed in a myriad of studies." (PMID 24971371, 2014). "Secondly, review of data for add-on therapy for patients with asthma not adequately controlled on ICS alone suggests that while cysLTR1 antagonists do appear to have benefit, the efficacy of the addition of LABA may be greater." (PMID 24971371, 2014). "It is also being increasingly recognized that cysLTR1 antagonists may have benefit in diseases beyond allergic rhinitis and asthma, some of which are described later, although none of these agents is currently registered for use in these conditions." (PMID 24971371, 2014).